FAM238B (family with sequence similarity 238 member B)
Synonyms: formerly LINC00202-2
Gene: Transcribed unprocessed pseudogene on chromosome 10 (26,650,554 to 26,653,383, forward strand). Ensembl gene ENSG00000231976.
Diseases named in the same sentence as FAM238B in open-access papers:
FAM238B is named in the same sentence as 1 disease in open-access papers, as found by Europe PMC text mining. Sharing a sentence is not in itself a finding about the gene and the disease.
FAM238B shares sentences with these, for which no sentence is quoted: neuropathy (1 paper).